FOXO3 (forkhead box O3)
Diseases named in the same sentence as FOXO3 in open-access papers (continued):
Sharing a sentence is not in itself a finding about the gene and the disease.
breast carcinoma (continued). "Our study demonstrated that CHIP-induced apoptosis resistance is closely associated with the AKT/FoxO3/Bim signaling pathway in both normal breast epithelial cell MCF10A and breast cancer cell MCF7 cells." (PMID 24376685, 2013). "A similar result has been reported in breast cancer that cytoplasmic expression of FOXO3 was related to shorter overall survival in patients." (PMID 23874926, 2013). "In contrast, upregulation of FOXO3 protein level by knocking down the expression of βTrCP1 in breast cancer cells suppresses their tumor growth in vivo." (PMID 20625400, 2010). "Using animal models, we further show that downregulation of FOXO3 protein level by ectopic expression of βTrCP1 in breast cancer cells promotes tumor proliferation or tumorigenesis." (PMID 20625400, 2010). "This study aimed to evaluate the interrelationship among silent information regulator (SIRT1), Forkhead box O3a (FoxO3a), and microRNA-34a (miR-34a), the latter of which promotes apoptosis by suppressing the proliferation, migration, and invasion of breast cancer cells." (PMID 41816745, 2025). "Propofol could inhibit the capacity of breast cancer cell stemness and proliferation by upregulation FOXO3, which inhibited SOX2 expression transcriptionally." (PMID 39991565, 2025). "During the prognosis of breast cancer, FOXO3 tends to be repressed and inactivated." (PMID 40003882, 2025). "This, in turn, leads to the reversal of the downregulation of FOXO3 in breast cancer." (PMID 40003882, 2025). "F. nucleatum promotes breast cancer cell migration through the miR-21-3p/FOXO3 pathway." (PMID 40589632, 2025). "For example, hsa_circ_0025202 acts as an oncogenic circRNA in human epidermal growth factor receptor 2 (HER2)-positive breast cancer by regulating the miR_182_5p/FOXO3a (forkhead box O3) axis and increasing the sensitivity of breast cancer to tamoxifen treatment." (PMID 40034125, 2025). "PML acting as a tumor suppressor in vivo inhibited normal cell apoptosis and differentiation, and it could regulate tumor suppressor FOXO3 to suppress the growth of breast cancer cells." (PMID 38750402, 2024). "Eugenol triggered apoptosis in breast cancer cells by regulating the AKT/FOXO3 pathway." (PMID 39334758, 2024). "HDAC3 facilitates FOXO3 deacetylation and breast cancer metastasis." (PMID 38466341, 2024). "NOC2L was found to be recruited by Enhancer of zeste homolog 2 (EZH2) and cooperate with EZH2 through physical interaction to promote the methylation of H3K27 in the vicinity of forkhead box O3 (FOXO3) promoter region, leading to the downregulation of tumor suppressor FOXO3 in breast cancer cells." (PMID 36650543, 2023). "This study’s objective was to assess circ-Foxo3 expression in breast cancer stem-like cells." (PMID 37400900, 2023). "Unfortunately, LINC00826 is downregulated in breast cancer tissue compared to healthy controls, and this downregulation is attributed to hypoxia-driven inhibition of forkhead box O3 (FOXO3A) dependent transcription of LINC00926, which results in advanced tumor growth and lung metastasis in vivo." (PMID 37583933, 2023). "In addition, FOXO3 exerted a higher expression level in breast cancer and was significantly correlated with a poor prognosis." (PMID 36292640, 2022). "Correlation study of FOXO3 mRNA expression levels with clinical parameters of breast cancer case." (PMID 36727057, 2022). "The relationship between decreased FOXO3 expression and advanced breast cancer stages may serve as a prognostic biomarker." (PMID 36727057, 2022). "SUMOylation might act to enhance FOXK2 transcriptional activity and mediate the cytotoxic response to paclitaxel through the tumour suppressor FOXO3 in breast cancer." (PMID 36172141, 2022). "Therefore, to provide better insight, our study aims to evaluate the role and function of FOXO3 in breast cancer in Indian female patients." (PMID 36727057, 2022).
breast carcinoma (continued). "In the case of Akt–FoxO signaling, the downregulation of p-Akt and FoxO3 expression could be a consequence of 7HF treatment, which could reduce the aggressiveness of breast cancer." (PMID 35056723, 2022). "In addition to these potential correlations, there was a significant (p=0.01) correlation between the lymph node status of patients with breast cancer and the FOXO3 gene expression." (PMID 36727057, 2022). "Correlation of FOXO3 protein expression level with clinical parameters of breast cancer patients." (PMID 36727057, 2022). "Through regulating FOXO3, miR-940 promotes malignant progression of breast cancer." (PMID 36467881, 2022). "Also, they showed that breast cancer cells transfected with Foxo3, Foxo3P, and circ-Foxo3 underwent extensive apoptosis." (PMID 34400888, 2021). "Moreover, miR-96 is known as a tumor suppressor in pancreatic cancer by suppressing KRAS, as well as in endometrial and breast cancers by suppressing FoxO1 and FOXO3 genes." (PMID 33788050, 2021). "In breast cancer cells, miRNA‐96‐5p functions as an oncogene by inhibiting FOXO3 expression." (PMID 32100957, 2020). "The role of FOXO3 protein in breast carcinogenesis may therefore depend on the subtype of breast cancer and the stage of disease." (PMID 32332845, 2020). "Besides SIRTs, the histone deacetylase HDAC3 has been shown to be specifically recruited by geminin to FOXO3 to facilitate FOXO3 deacetylation and breast cancer metastasis." (PMID 32372224, 2020). "In addition, we found that FOXO3 spoiled miR‐96‐5p induced breast cancer cell proliferation block effecting." (PMID 32100957, 2020). "FOXO3, as a member of the forkhead type transcription factor family, is a tumor suppressor often deregulated in different types of human cancers, including prostate cancer, pancreatic cancer and breast cancer." (PMID 32840296, 2020). "SIRT6 also represses FOXO3 acetylation to promote clonal renewal and survival in breast cancer." (PMID 32372224, 2020). "circRNAs deriving from the FOXO3 gene have previously been demonstrated to regulate cell cycle when manipulated by gene knockdown in mouse embryonic fibroblasts, cardiac fibroblasts or mammary cancer cell lines." (PMID 31811527, 2020). "Importantly, LINC01355-mediated suppression of breast cancer growth was reversed by knockdown of FOXO3 or overexpression of CCND1." (PMID 31243265, 2019). "We have previously shown that HER2 expression can promote FOXO3 cytoplasmic localisation via activating AKT, and this could account for the observation that 95.7% of the 447 HER2+ breast cancer cases have cytoplasmic FOXO3 expression." (PMID 31312024, 2019). "Moreover, FOXO3 is known to be able to induce G1 and G2/M phase cell cycle arrest and apoptosis in breast cancer cells treated with paclitaxel." (PMID 30917517, 2019). "This adaptive dependence on higher PERK activity to combat elevated ER-stress coupled to the intrinsically low PERK levels as a result of low expression and activity of its regulator FOXO3 in these drug-resistant breast cancer cells renders them particularly vulnerable to PERK inhibition." (PMID 31312024, 2019). "FOXO3 has been shown to control various aspects of breast cancer biology." (PMID 31243265, 2019). "A recent study suggests that FOXO3 both suppresses and supports breast cancer progression." (PMID 31488102, 2019). "The high cytoplasmic FOXO3 expression rates in this panel of HER2+ breast cancer samples could also be the reason why a good correlation analysis between PERK and cytoplasmic FOXO3 expression can be made." (PMID 31312024, 2019). "Next, we examined the effect of LINC01355 on the expression of FOXO3 in breast cancer cells." (PMID 31243265, 2019). "Therefore, FOXO3 acetylation, regulated coordinately by EP300 and sirtuins, is an important PTM which regulates FOXO3 expression and transcriptional activity to modulate lapatinib sensitivity in breast cancer." (PMID 31357743, 2019).
breast carcinoma (continued). "As an example, in breast cancer, FOXO3 activation correlates with VEGFA downregulation." (PMID 30842454, 2019). "Along this way, a deregulation of the canonical Mitogen-Activated Protein Kinase (MAPK)/Erk1/2 pathway was identified in breast cancer and in Hodgkin’s lymphoma, whereas the Ikk pathway emerged in acute myeloid leukemia and lung cancer as an important regulator of FoxO3." (PMID 30646603, 2019). "In agreement with a previous report that BRCA1 acts as a pivotal suppressor of EZH2 in the PRC2 complex 42, it has been shown recently that EZH2 represses expression of FOXO3, but this regulation only occurs when EZH2 becomes hyperactivated in BRCA1-deficient breast cancer cells." (PMID 31410199, 2019). "Recent publication suggests that FOXO3 can both suppress and support breast cancer progression." (PMID 31488102, 2019). "In breast cancer, downregulated circ-Foxo3 can enhance cell survival and decrease cell apoptosis." (PMID 30126353, 2018). "In addition, we have also demonstrated that FOXO3 plays a key role in mediating the cytotoxic function of FOXK2 in response to paclitaxel in breast cancer cells." (PMID 29540677, 2018). "Overexpression of FOXO1 and FOXO3 has been shown to inhibit the growth of breast cancer cells." (PMID 29484124, 2018). "Some of them may have antitumor activity, such as ergosterol, which can reduce the breast cancer cell viability through induction of apoptosis and up-regulation of Foxo3 expression." (PMID 30595979, 2018). "circ-Foxo3 is a potential tumor suppressor that is significantly downregulated in breast cancer tissues and may be involved in tumor progression." (PMID 30064463, 2018). "Furthermore, similar to our finding, earlier reports suggest that activation of Akt and Erk promotes cancer progression via downregulation of FOXO3 in breast cancer and uveal melanoma cancer cells." (PMID 29915392, 2018). "Many observations indicate that FOXO3 also exerts tumour suppressor activity in breast cancer." (PMID 29484124, 2018). "Accordingly, FOXK2 mediates drug sensitivity in breast cancer cells in a FOXO3-dependent fashion." (PMID 29540677, 2018). "Additionally, TiHo-0906 cells at low and high passage also displayed CNGs in regions harbouring other known breast cancer-related genes like FOXO3 and MYB (FCA B2), AKT1 (FCA B3), and GATA-3, CCND2, CDK4 and PFDN5 (FCA B4)." (PMID 30185896, 2018). "Beside circ-Foxo3, circ-ABCB10 is another circRNA associated with breast cancer." (PMID 29349062, 2017). "Also, mouse xenograft models for breast cancer showed arrested tumor growth in the presence of circ-Foxo3 due to apoptosis, induced through combining circ-Foxo3, Foxo3P, and Foxo3 activity, when compared to controls." (PMID 29349062, 2017). "Statistical analysis of the methylation profiles of FOXO3 promoter in these familial breast cancers revealed that FOXO3 methylation levels were significantly higher in BRCA1-mutated tumours, compared with BRCA2-, BRCAx- and BRCA2/x-mutated tumours (P=0.019, P=0.053 and P=0.026, respectively)." (PMID 27043660, 2016). "Collectively, these data provide evidence that FOXO3 is methylated in basal subtype breast cancers, where BRCA1 is either mutated or depleted, highlighting the importance of BRCA1 in promoting FOXO3 expression through suppressing FOXO3 methylation in luminal breast cancers." (PMID 27043660, 2016). "A study from 2013 revealed that a high expression level of FOXO3 was significantly correlated with long-term survival, indicating that FOXO3 expression is a favorable prognostic marker in breast cancer and this may also be applicable for dogs." (PMID 27657059, 2016). "The correlation between BRCA1 and FOXO3 expression in the panel of breast cancer cell lines led us hypothesize that BRCA1 regulates FOXO3 expression." (PMID 27043660, 2016).
breast carcinoma (continued). "In addition, the Foxo3 down-stream signaling molecules Fas, FasL, BimL, and BimS were up-regulated leading to apoptosis in human breast cancer cells MDA-MB-231." (PMID 26098777, 2015). "This study aimed to investigate the role of forkhead box O3 (FOXO3a) in breast cancer cells and examine the regulatory mechanisms of FOXO3a in response to casticin treatment of the cells by ELISA, flow cytometry, small interfering RNA (siRNA) transfection and western blot analysis." (PMID 24765206, 2014). "In addition, FOXO3 overexpression was shown to reduce motility, invasiveness, and aggressiveness in estrogen receptor α-positive (ERα+) breast cancer cells." (PMID 32309538, 2013). "Also, increased expression of miR-96 in breast cancer cells have been shown to downregulate FOXO3 transcription factor with consequent induction of cell proliferation." (PMID 32309538, 2013). "Moreover, in breast cancer cells, E-cadherin inactivation may lead to FOXO3 inhibition in a PI3K/AKT-dependent manner." (PMID 40003882, 2025). "Additionally, the majority of samples exhibit nuclear staining of the protein, and the proportion of FOXO3 protein down-regulation was significant with breast cancer III and IV stages, oestrogen receptor, tumour size, molecular subtype, and highly significant lymph node status." (PMID 36727057, 2022). "Moreover, Met also has an anti-proliferative effect in breast cancer via activating FOXO3." (PMID 34546972, 2021). "Indeed, anoikis has been shown to be regulated by FOXO3 activity during breast cancer metastasis." (PMID 32372224, 2020). "Therefore, one of the mechanisms by which FOXO3 protein could inhibit DDR in breast cancer, would be the inhibition of the transcription of DDR-genes induced by FOXM1." (PMID 32332845, 2020). "In addition, the expression levels of FOXO3 and FOXA1 may also be useful biomarkers to molecularly classify BRCA1-mutated breast cancers." (PMID 27043660, 2016). "Indeed FOXO3 has been observed in breast cancer and does play a role in apoptosis." (PMID 23950968, 2013). "such as interaction of FOXO3 protein with LINC01355 stabilizes FOXO3 and in turn inhibits CCND1 transcription and hence breast cancer growth." (PMID 39912983, 2025). "This suggests that FOXO3 is a pivotal effector of both PI3Kαi and AKTi in PIK3CA altered breast cancer." (PMID 40263319, 2025). "The reprogrammed pDCs then promote Treg expansion by expressing forkhead box O3 (FOXO3) and inducible costimulatory molecule ligands, and therefore pDCs infiltration is correlated with poor prognosis in breast cancer patients." (PMID 40165290, 2025). "In particular, FOXC1, FOXM1, and FOXO3 can all interact with BRCA1 and regulate the genome stability of breast cancer cells." (PMID 40003882, 2025). "For example, FOXA1, FOXA2, FOXC1, and FOXO3 can all interact with the PI3K/AKT/mTOR pathway and eventually regulate breast cancer cell proliferation." (PMID 40003882, 2025). "Predictions of known cancer driver genes in new cancer types include SPTA1, CHD4 and ASXL1 in colorectal cancer, FOXO3, MUC16 and ZFPM1 in breast cancers and CNTNAP2, CTNND2 and TRRAP in lung adenocarcinoma." (PMID 38890488, 2024). "Crocin induced apoptosis in breast cancer cells by generating ROS, involving the PTEN/AKT/FOXO3 signaling pathways." (PMID 39334758, 2024). "Similar findings have been reported for the forkhead box O3 (FOXO3)-mediated phosphorylation and activation of PERK, which lead to drug resistance to epirubicin and tamoxifen in breast cancer cells." (PMID 38474017, 2024). "JNK phosphorylates FoxO3 and promotes its translocation into the cell nucleus, and RHBDF1 activates JNK in breast cancer cells." (PMID 39420837, 2024). "They demonstrated that ectopic expression of circ-Foxo3 drastically reduced cell proliferation and survival of the MDA-MB-231 breast cancer cell line." (PMID 37400900, 2023).
breast carcinoma (continued). "When GPNMB-positive cells form spheres in breast cancer, the expression levels of CSC markers such as SOX2, NANOG, OCT4, CD44, CD133, and FOXO3 are elevated." (PMID 36061142, 2022). "P300 catalyzes the acetylation of Forkhead Box O3 (FOXO3) to promote its nuclear translocation and activation, thus increasing the cytotoxicity of Lapatinib in HER2 positive breast cancer cells." (PMID 35216622, 2022). "The expression level of FOXO3 mRNA was observed to be downregulated in 66.14% of cases (84/127), of which 72.6% (61/84) fell into the III and IV stages of breast cancer." (PMID 36727057, 2022). "AKT phosphorylation by AEG-1 induced enhanced cell survival and proliferation through the suppression of forkhead box O3A (FOXO3A) activity in prostate cancer and FOXO1 in breast cancer." (PMID 33918653, 2021). "Recent experimental and clinical studies have investigated that FOXO3 and FOXO4 play an important role in the progression of breast cancer, pancreatic cancer, and other cancers." (PMID 34055579, 2021). "Similar to our study, the authors found upregulation of the hypoxia-related genes ENO1, FOXO3, VEGF, LDH, and NPRG1 in recurrent patients with high grade breast cancer tumors." (PMID 33804802, 2021). "For example, neddylation inactivation by the specific inhibitor MLN4924 can prevent FOXO3 nuclear export, decrease its binding to the ESR1 (oestrogen receptor) gene promoter and improve fulvestrant sensitivity in breast cancer." (PMID 32372224, 2020). "We have also found that FOXO3 regulates PERK expression and that PERK expression is attenuated as a result of the adaptative lower FOXO3 expression in the drug-resistant breast cancer cells." (PMID 32615282, 2020). "Contrarily, FOXO3 activation promotes tumor cell invasion through the upregulation of matrix metalloproteinase-9 (MMP-9) and MMP-13 levels in breast cancer cells." (PMID 32629884, 2020). "In support of our finding, we also uncover that there is also a strong and significant correlation between FOXO3 and PERK mRNA levels in the Cancer Genome Atlas (TCGA) breast cancer patient datasets." (PMID 31312024, 2019). "FOXO3 promotes cell invasion through the induction of the matrix metalloproteinases MMP-9 and MMP-13 in breast cancer cells." (PMID 31861249, 2019). "Consistent with this, in here we find FOXO3 expression and activity to be downregulated in epirubicin and paclitaxel-resistant MCF-7 breast cancer cells." (PMID 31312024, 2019). "In this study, using the BT474 breast cancer cells and a recently established lapatinib resistant (BT474-LapR) cell line, we observed that higher FOXO3 and acetylated (Ac)-FOXO3 levels correlate with lapatinib sensitivity." (PMID 31357743, 2019). "Consistent with the finding that knockdown of FOXO3 abrogates LINC01355-induced downregulation of CCND1, FOXO3 depletion reverses the inhibitory effect of LINC01355 on breast cancer cell proliferation and tumorigenesis." (PMID 31243265, 2019). "The present study indicated another type of crosstalk in which ESR1 and FOXO3 interact and are co-upregulated in the nucleus of LTED cells, which serve as a model for endocrine therapy-resistant breast cancer." (PMID 31439835, 2019). "Our results propose that PMLIV overexpression inhibits the proliferation of breast cancer cells by concurrently regulating the oncogenic transcription factor FOXM1 and the tumor suppressor FOXO3 that acts upstream of FOXM1." (PMID 30927552, 2019). "With this in mind, we exploit this adaptive response of low FOXO3 and PERK expression, and high PERK activity in drug-resistant breast cancer cells and show that these drug-resistant cells are specifically sensitive to PERK inhibition." (PMID 31312024, 2019).